KIT (KIT proto-oncogene, receptor tyrosine kinase)
Diseases named in the same sentence as KIT in open-access papers (continued):
Sharing a sentence is not in itself a finding about the gene and the disease.
gastrointestinal stromal tumor (continued). "The mutation of the KIT (KIT-proto-oncogene receptor tyrosine kinase) gene, which is characteristic of mucosal melanomas, can be detected in melanomas of the skin at a much lower rate (~5%), involving more exons compared to GIST (gastrointestinal stromal tumors)." (PMID 40361349, 2025). "Unlike gastrointestinal stromal tumors (GISTs), where activating KIT mutations are common, mutations in the juxtamembrane or tyrosine kinase domains of KIT have not been identified in AS." (PMID 40666093, 2025). "In contrast, KIT alterations in gastrointestinal stromal tumors are more homogeneous, with 70%–90% being exon 11 deletions, and potentially relatedly, KIT inhibitors are an effective standard of care across most patients with KIT-mutated gastrointestinal stromal tumors." (PMID 38417447, 2024). "Gastrointestinal stromal tumor (GIST), commonly occurring in the gastrointestinal tract, is a mesenchymal cell tumor usually driven by activating mutations in the receptor tyrosine kinase proto-oncogene, KIT, or the platelet-derived growth factor receptor α (PDGFRα)." (PMID 39834833, 2024). "Gastrointestinal stromal tumors lacking the KIT/PDGFRA mutations, however, represent distinct clinico-pathological entities with diverse molecular mechanisms of oncogenesis." (PMID 36900287, 2023). "The proto-oncogene KIT encodes the type III receptor tyrosine kinase c-KIT, which plays a crucial role in several malignant neoplasms, including gastrointestinal stromal tumors (GISTs), chronic myeloid leukemia (CML), mastocytosis, melanoma, and germ cell tumors." (PMID 37849766, 2023). "Imatinib, for example, which has led to a significant increase in CML survival rates by selectively targeting the tumor-specific protein BCR/ABL, was included for the treatment of gastrointestinal stromal tumors (GIST), which are characterized by KIT-activating mutations." (PMID 36839989, 2023). "Primary double KIT/PDGFRA mutations are very rare in gastrointestinal stromal tumours (GISTs) but have not been comprehensively studied to date." (PMID 36890498, 2023). "KIT/PDGFRA wild type gastrointestinal stromal tumors (wtGIST) account for the remaining 15% of GIST and represent an unmet medical need: their prevalence and potential medical vulnerabilities are not completely defined, and effective therapeutic strategies are still lacking." (PMID 36142281, 2022). "Four out of six gastrointestinal stromal tumors (GIST) had a KIT exon 11 deletion." (PMID 35053600, 2022). "Primary leiomyosarcoma of the stomach is extremely rare, and most cases reported as leiomyosarcoma of the stomach before the development of KIT immunohistochemistry (pre-KIT era) might be gastrointestinal stromal tumors (GISTs) of the stomach." (PMID 34143361, 2021). "To date, a substantial effort has been focused on targeting KIT by small molecule inhibitor imatinib, having dramatic activity against chemoresistant sarcoma and gastrointestinal stromal tumors, in which the clinical response correlates with the type of KIT mutations." (PMID 34639089, 2021). "Previous research has shown that KIT is altered in gastrointestinal stromal tumors." (PMID 33869179, 2021). "Recently, enhancer domains of the KIT gene have been shown to be targetable by BET bromodomain inhibition in gastrointestinal stromal tumors, thus defining therapeutic vulnerability and the clinical strategy for targeting oncogenic kinases by the new generation of epigenetic drugs." (PMID 34639089, 2021). "Most cases reported as leiomyosarcoma of the stomach before the development of KIT immunohistochemistry might be gastrointestinal stromal tumors (GISTs) of the stomach and only 18 cases of leiomyosarcoma of the stomach have been reported since early 2000s." (PMID 34143361, 2021).
gastrointestinal stromal tumor (continued). "Lastly, the single-dose administration (20 mg/kg) of two novel anti-c-KIT antibody–drug conjugates, with novel NAMPT inhibitors as payloads, efficiently blocked in vivo tumor proliferation in c-Kit-positive gastrointestinal stromal tumor GIST-T1 mouse xenografts." (PMID 34068917, 2021). "Gastrointestinal stromal tumors (GISTs) associated with SDH deficiency are negative for KIT/PDGFRA mutations and present with distinctive clinical features such as early onset (usually childhood or adolescence) and almost exclusively gastric location." (PMID 34012423, 2021). "More examples of predictive molecular biomarkers routinely tested in clinical settings include the following: KIT/PDGFRA in gastrointestinal stromal tumors, BRAF/NRAS/KIT in advanced melanoma, IDH1/1p/19q codeletion/MGMT promoter methylation in brain neoplasms." (PMID 33670699, 2021). "Gastrointestinal stromal tumours that are wild type for KIT and PDGFRA are referred to as WT GISTs." (PMID 33199729, 2020). "Gastrointestinal stromal tumor (GIST) is a common intestinal mesenchymal neoplasm of the gastrointestinal tract that is mainly characterized by the overexpression of receptor tyrosine kinase KIT." (PMID 32393233, 2020). "Aberrant KIT signaling in MCT can be due to activating mutations, similar to those found in gastro-intestinal stromal tumors in humans, consisting of internal tandem duplications in the juxtamembrane domain of KIT which results in constitutive receptor phosphorylation." (PMID 32411603, 2020). "Gastrointestinal stromal tumor (GIST) is frequently driven by oncogenic KIT variations." (PMID 32986105, 2020). "Gastrointestinal stromal tumours (GISTs), the most common mesenchymal neoplasm of the gastrointestinal tract, result from deregulated proliferation of transformed KIT‐positive interstitial cells of Cajal that share mesenchymal progenitors with smooth muscle cells." (PMID 32633461, 2020). "To evaluate if these results are generalizable to other cancer types and primary tumor samples, we tested the effect of imatinib on the KIT-mutant gastrointestinal stromal tumor (GIST) cell line GIST-T1 and the effects of gefitinib on the EGFR-mutant lung cancer cell line PC9." (PMID 31727958, 2019). "An identified KIT mutation led to the “off-label” use of imatinib, but despite promising data from the gastrointestinal stromal tumor (GIST), the patient did not achieve a positive clinical response." (PMID 30410678, 2018). "Gastrointestinal stromal tumour (GIST) is the most common primary mesenchymal tumour of the gastrointestinal tract and spans a clinical spectrum from benign to malignant; most cases contain KIT- or PDGFRA-activating mutations." (PMID 28386296, 2017). "MiR-494 is an oncomiR in gastrointestinal stromal tumors that targets the KIT proto-oncogene." (PMID 27575252, 2016). "Gastrointestinal stromal tumors (GISTs) with no mutations in exons 9, 11, 13, and 17 of the KIT gene and exons 12, and 18 of the PDGFRA gene were defined as KIT/PDGFRA wild-type and they accounted for ~15–20% of GISTs." (PMID 26848617, 2016). "Gastrointestinal stromal tumors (GIST) are among the most commonly diagnosed mesenchymal tumors and are typically characterized by gain of function mutations in receptor tyrosine kinases (RTKs) KIT or PDGFRA." (PMID 27167336, 2016). "Interestingly, it also can function as a tumor suppressor-miR in other cancer types, for example, in erythroblastic leukemia, and gastrointestinal stromal tumors, miR-222 inhibits cell growth and induces apoptosis by targeting KIT and ETV1." (PMID 27811362, 2016). "Gastrointestinal stromal tumors (GISTs) develop within the digestive tract and harbor functional mutations of KIT (v-kit Hardy-Zuckerman 4 feline sarcoma viral oncogene homolog) and PDGFRA (platelet-derived growth factor receptor-α) that primarily drive the tumor growth and progression." (PMID 26867653, 2016).
gastrointestinal stromal tumor (continued). "Additionally, imatinib is also a potent antagonist of c-kit receptor tyrosine kinase (c-KIT) and platelet-derived growth factor receptor A (PDGFRA) kinase, both of which cause gastrointestinal stromal tumors (GIST)." (PMID 26370727, 2015). "The postulated relationship between KIT/PDGFRA mutations and their prognostic value in gastrointestinal stromal tumors (GISTs) has generated intense attention during the past decade, despite the fact that a great deal of studies have been conducted on this subject." (PMID 24674052, 2014). "In addition, a recent study suggests that IDO1 is also driven by oncogenic KIT signaling in gastrointestinal stromal tumors (GIST)." (PMID 25628622, 2014). "Extraction of DNA from cellular tumors with a solid growth pattern and little contaminating, non-neoplastic tissue is relatively easy, as with gastrointestinal stromal tumors for identification of the KIT mutations." (PMID 25067909, 2014). "Although KIT inhibitors such as Imatinib are effective for KIT juxtamembrane mutations frequent in gastrointestinal stromal tumors, Imatinib fails to bind and inhibit KIT D816V kinase." (PMID 25026279, 2014). "Gastrointestinal stromal tumors (GISTs) are the most common mesenchymal neoplasms of the gastrointestinal system, characterized by an unique histological morphology and the expression of the KIT protein." (PMID 24548660, 2014). "In addition to its use in CML, imatinib also plays a role in gastrointestinal stromal tumor (GIST) formation as it also inhibits the c-KIT and PDGFR tyrosine kinases." (PMID 25191874, 2014). "Gastrointestinal stromal tumors (GISTs) lacking of KIT and PDGFRα mutations presented significantly higher prevalence of IGF-1R amplification compared to mutated ones." (PMID 22415797, 2012). "Targeting the tyrosine kinase KIT in gastrointestinal stromal tumors has led to improved treatment." (PMID 21559261, 2011). "Interesting data have been reported also on IGF1r in gastrointestinal stromal tumors (GISTs) especially in children and in young adult patients whose disease does not harbour mutations on KIT and PDGFRA and are poorly responsive to conventional therapies." (PMID 21078151, 2010). "Epithelioid tumor pattern, weak or absent KIT expression and detection of PDGFRalpha mutation are typical diagnostic parameters of gastric gastrointestinal stromal tumors." (PMID 19830214, 2009). "As a result, dasatinib may also have a role to play in diseases associated with KIT activation loop mutations such as systemic mastiocytosis, acute myelogenous leukaemia (AML), seminoma, gastrointestinal stromal tumours and anal melanomas." (PMID 18929568, 2009). "Emergency local excision with negative margins associated with adjuvant therapy with KIT tyrosine kinase inhibitor remains the main modality of treatment for high risk gastrointestinal stromal tumors." (PMID 18627622, 2008). "Gastrointestinal stromal tumours (GISTs) are non-epithelial tumours of the gastrointestinal tract that are commonly caused by activating or gain-of-function mutations in the KIT gene." (PMID 17519908, 2007). "KIT is expressed in normal cells and also in solid tumors and hematological malignancies such as gastrointestinal stromal tumor (GIST), small-cell lung cancer, colorectal cancer, Ewing's tumor, chronic myelogenous leukemia (CML), neuroblastoma and mast cell leukemia." (PMID 17044945, 2006). "Gastrointestinal stromal tumor (GIST) is defined as the most common soft tissue sarcoma (STS) of the gastrointestinal tract and featured with activating mutations in KIT or, less commonly, PDGFRA1." (PMID 41510151, 2026). "Inhibition of RET and KIT supports its therapeutic role in thyroid cancers and gastrointestinal stromal tumors (GIST), particularly in the context of resistance to earlier-generation TKIs." (PMID 41517566, 2026).
gastrointestinal stromal tumor (continued). "In gastrointestinal stromal tumors (GIST), abnormal expression of the c-KIT gene is a key factor in tumor occurrence and development, and the G4 structure in the c-KIT promoter region has become a potential regulatory target." (PMID 40426885, 2025). "When an activating KIT mutation is observed in TET, KIT inhibitors such as imatinib, sunitinib, or sorafenib, based on the sensitivity to these inhibitors reported in other cancers, like gastro-intestinal stromal tumors, may be considered." (PMID 40434678, 2025). "ctDNA sequencing efficiently detects KIT/PDGFRA mutations and prognosticates outcomes in patients with TKI‐resistant gastrointestinal stromal tumor (GIST) treated with avapritinib." (PMID 40656546, 2025). "Avapritinib showed clinical activity against PDGFRA D842V‐mutant and later‐line KIT‐mutant gastrointestinal stromal tumors (GIST)." (PMID 40656546, 2025). "Tier IB predictors were identified in NB (ALK aberrations, 31 patients) and gastrointestinal stromal tumor (GIST, KIT amplification, one patient)." (PMID 41373618, 2025). "Pathogenic variants in SDHx genes, initially considered as susceptibility genes only for PPGLs, are in fact also recognized to be associated with a risk of renal cancer and wild GIST (gastrointestinal stromal tumors without mutation in the KIT and PDGFRA genes)." (PMID 39457697, 2024). "In a KIT-driven mouse model of gastrointestinal stromal tumor (GIST), γδ T cells were activated and highly expressed programmed cell death protein-1 (PD-1) and secreted IL-17." (PMID 39748921, 2024). "A gastrointestinal stromal tumor (GIST) is a mesenchymal neoplasm of the gastrointestinal tract often known to express c-KIT or platelet-derived growth factor receptor alpha (PDGFRα)." (PMID 36874698, 2023). "Gain-of-function mutations KIT and PDGFRA tyrosine kinases (TK) are responsible for between 85 and 90% of gastrointestinal stromal tumors (GIST), with the latter occurring only in approximately 5–10% of cases." (PMID 36293105, 2022). "Chinese consensus guidelines for diagnosis and management of gastrointestinal stromal tumor recommend KIT/PDGFRA gene testing for CD117/DOG1-negative GIST patients, which acts as a supplement for immunohistochemical diagnosis." (PMID 35547262, 2022). "KIT is already an established therapeutic target agent in other cancers, specifically in gastrointestinal stromal tumors (GIST)." (PMID 35159047, 2022). "In the case of KIT-mutant melanomas, it is important to define the KIT-inhibitor sensitive ones based on experiences with KIT inhibitor efficacy in gastrointestinal stromal tumor (GIST)." (PMID 35628196, 2022). "Imatinib has been approved by the Food and Drug Administration (FDA) for the treatment of chronic myelogenous leukemia (CML) and gastrointestinal stromal tumors (GIST) expressing KIT." (PMID 34944814, 2021). "The gastrointestinal stromal tumor (GIST) is a potentially malignant mesenchymal tumor (sarcoma) that usually expresses KIT or DOG1 proteins by immunohistochemistry (IHC)." (PMID 34202544, 2021). "It is very important to establish the relationship among gene mutations, treatment, and prognosis, especially for driver or key genes, since this may suggest targets for more effective drugs in clinical practice such as EGFR in lung cancer and KIT in gastrointestinal stromal tumors." (PMID 34368001, 2021). "KIT overexpression has been reported in thymic carcinoma, gastrointestinal stromal tumor (GIST), chronic myeloid leukemia (CML), mastocytosis, germ cell tumors such as seminoma, and malignant melanoma." (PMID 34680386, 2021). "Imatinib, which has multiple therapeutic targets including BCR-ABL, KIT, and the platelet-derived growth factor receptor (PDGFR), was approved for the treatment of gastrointestinal stromal tumors (GIST) (the majority of these tumors have the KIT mutation)." (PMID 34831002, 2021).
gastrointestinal stromal tumor (continued). "The therapeutic effect of imatinib, a tyrosine kinase inhibitor, in gastrointestinal stromal tumors (GIST) is also associated with downregulation of IDO1 expression, which, in turn, is driven by the oncogenic tyrosine-protein kinase KIT signaling." (PMID 34201791, 2021). "Numerous inhibitors of tyrosine-protein kinase KIT, a receptor tyrosine kinase, have been explored as a viable therapy for the treatment of gastrointestinal stromal tumor (GIST)." (PMID 33851030, 2021). "Imatinib is a FDA-approved treatment for gastrointestinal stromal tumors which are driven by c-KIT mutations in >80% of cases, chronic myelogenous leukemia where it targets the aberrant BCR-ABL kinase, and in select metastatic melanoma tumors with activating c-KIT mutations." (PMID 34063789, 2021). "However, prior to the late 1990s when KIT staining became widely available, most gastrointestinal stromal tumors were diagnosed with leiomyosarcoma based on histological criteria, and older reports on leiomyosarcoma mainly consisted of patients with gastrointestinal stromal tumors." (PMID 32648686, 2020). "The KIT gene encodes the stem cell growth factor receptor, a type III transmembrane receptor tyrosine kinase that has been involved in the pathogenesis of various malignancies, including gastro-intestinal stromal tumours, acute myelogenous leukaemia and testicular seminomas." (PMID 33187494, 2020). "Inhibition of KIT-signaling is a major molecular target for gastrointestinal stromal tumor (GIST) therapy, and imatinib mesylate (IM) is known as the most effective first-line treatment option for patients with advanced, unresectable, and/or metastatic GISTs." (PMID 32599808, 2020). "Gastrointestinal stromal tumor (GIST) is the most common sarcoma and is frequently driven by oncogenic KIT (OMIM 164920) variations." (PMID 32986105, 2020). "KIT proto-oncogene takes part in fertility, homeostasis, and melanogenesis, while the dysregulation of KIT has been found to participate in the occurrence of leukemia, gastrointestinal stromal tumor (GIST), melanoma, and other cancers." (PMID 33109256, 2020). "Imatinib is an approved inhibitor of BCR-ABL, and KIT tyrosine kinase is used in the treatment of Philadelphia chromosome-positive chronic myeloid leukemia (CML) and KIT-positive gastrointestinal stromal tumors (GIST), respectively." (PMID 32806706, 2020). "On the other hand, imatinib is also a potent antagonist of c-kit receptor tyrosine (c-KIT) and PDGFRA kinases, both of which cause gastrointestinal stromal tumors (GIST)." (PMID 30836705, 2019). "Succinate dehydrogenase (SDH)-deficient gastrointestinal stromal tumors (GISTs) constitute a small KIT/PDGFRA-WT GIST subgroup featuring DNA methylation which, although pervasive, appears nevertheless not randomly distributed." (PMID 30616628, 2019). "Permanently active KIT mutations lead these host cells to tumorigenesis, and to such diseases as mast cell leukemia (MCL), gastrointestinal stromal tumor (GIST), and acute myeloid leukemia (AML)." (PMID 31484543, 2019). "95% of gastrointestinal stromal tumors (GIST) exhibit an overexpression of the receptor tyrosine kinase KIT." (PMID 29451912, 2018). "Gastrointestinal stromal tumors (GIST) are uncommon mesenchymal tumors arising from the interstitial cells of Cajal, which express KIT protein-CD117 on immunohistochemistry." (PMID 28638830, 2017). "Gastrointestinal stromal tumor (GIST) is the most common sarcoma, often resulting from a KIT or platelet-derived growth factor receptor alpha (PDGFRA) mutation." (PMID 29371979, 2017). "Constitutive and ligand-derived signaling pathways mediated by KIT and PDGFRA mutated proteins found in gastrointestinal stromal tumors (GIST) were compared." (PMID 27872880, 2016).